TTTY17B (testis expressed transcript, Y-linked 17B)
Synonyms: NCRNA00141
Gene: Long non-coding RNA gene on chromosome Y (24,485,332 to 24,486,463, forward strand). Ensembl gene ENSG00000227439.
Homologues: Paralogues in human: TTTY17A (100% identical).